EDA2R (ectodysplasin A2 receptor)
Description:
Receptor for EDA isoform A2, but not for EDA isoform A1. Mediates the activation of the NF-kappa-B and JNK pathways. Activation seems to be mediated by binding to TRAF3 and TRAF6.
Synonyms: TNFRSF27; XEDAR; EDA-A2R; EDAA2R
Tractability: Antibody: its Gene Ontology location is reachable by antibodies, with high confidence; UniProt predicts a signal peptide or a membrane-spanning region.
Gene: Protein-coding gene on chromosome X (66,594,384 to 66,639,298, reverse strand). Ensembl gene ENSG00000131080.
Subcellular location: Membrane
Subcellular location (Human Protein Atlas): Cell Junctions
Pathways (Reactome):
Immune System: TNFs bind their physiological receptors
Gene Ontology:
Molecular function: protein binding; transmembrane signaling receptor activity; tumor necrosis factor receptor activity; signaling receptor activity
Biological process: cytokine-mediated signaling pathway; positive regulation of canonical NF-kappaB signal transduction; positive regulation of JNK cascade; ectodermal cell differentiation; epidermis development; tumor necrosis factor-mediated signaling pathway
Cellular component: plasma membrane; membrane
Homologues: Orthologues: chimpanzee EDA2R (99% identical), macaque EDA2R (93% identical), mouse Eda2r (80% identical), rat Eda2r (80% identical), rabbit EDA2R (63% identical), guinea pig EDA2R (51% identical), tropical clawed frog eda2r (35% identical). Paralogues in human: TNFRSF19 (32% identical), EDAR (21% identical).
Diseases named in the same sentence as EDA2R in open-access papers:
EDA2R is named in the same sentence as 60 diseases in open-access papers, as found by Europe PMC text mining. Sharing a sentence is not in itself a finding about the gene and the disease. The quoted sentences say what the papers report.
androgenetic alopecia (7 papers, 2009 to 2025). "Our findings align with human study where a non-synonymous SNP mutation (rs1385699, p = 3 × 10− 9) of EDA2R is strongly associate with androgenetic alopecia, suggesting evolutionary conservation of this pathway in animal pelage development." (PMID 41257555, 2025). "In fact our group was able to identify a variant related to the EDA2R gene strongly associated with Androgenetic Alopecia showing an average prevalence of 47% in the 8 villages." (PMID 19247500, 2009). "Importantly, such intergenic polymorphisms, particularly those located between the AR and EDA2R genes, may influence the expression of both genes and simultaneously associate with male‐pattern baldness." (PMID 41185962, 2025). "Onset of male pattern baldness could be influenced by EDA2R via activation of nuclear proto-oncoprotein c-Jun, which is linked to transcription activation of AR." (PMID 28196072, 2017). "Eda2r is a single-pass transmembrane receptor of the TNF family, located near AR on the X-chromosome, and is linked to several overlapping features of patients with SBMA or AR biology, including aging, metabolic dysfunction, dysregulation of hair growth (androgenic alopecia), and muscle atrophy." (PMID 38973610, 2024).
breast carcinoma (3 papers, 2021 to 2023). "The results revealed that elevated EDA2R expression was associated with lower overall survival in patients with breast cancer." (PMID 37904416, 2023). "Survival curves revealed that higher levels of EDA2R transcription were linked to poorer overall survival in breast cancer, stomach adenocarcinoma, head and neck squamous cell carcinoma, and cervical squamous cell carcinoma." (PMID 37904416, 2023). "EDA2R, a tumor necrosis factor receptor, is downregulated in breast cancer through promoter methylation, which binds to ectodysplasin-A2 and induces cell deaths." (PMID 35186006, 2021). "We observed that EDA2R, MAP3K4, and WWOX exhibited reduced mRNA expression in 1,085 breast cancer tissues compared with 291 normal breast tissues." (PMID 35186006, 2021).
Cachexia (3 papers, 2023 to 2026). Severe weight loss, wasting of muscle, loss of appetite, and general debility related to a chronic disease. "Collectively, these studies establish EDA2R as a central mediator of muscle wasting in both sarcopenia and cachexia and highlight its potential as a therapeutic target to mitigate muscle degeneration associated with ageing and chronic illness." (PMID 41185962, 2025). "The researchers found that Eda2r was significantly upregulated in type IIb myonuclei during cachexia, correlating with increased expression of atrophy‐related genes such as Atrogin1 and MuRF1." (PMID 41185962, 2025). "Crucially, Eda2r‐knockout mice were resistant to tumour‐induced muscle wasting, preserving muscle mass and function, highlighting the critical role of the EDA‐A2–EDA2R–NIK pathway in cachexia‐associated muscle atrophy." (PMID 41185962, 2025).
dementia (3 papers, 2025). Loss of intellectual abilities interfering with an individual's social and occupational functions. "In our study, although the significant findings for KIM1 and EDA2R attenuated after full adjustments, MR analyses showed some possible causal links between these proteins and dementia." (PMID 40092369, 2025). "Furthermore, Mendelian randomisation analysis provided evidence supporting a potential causal link between circulating EDA2R levels and both Alzheimer's disease and all‐cause dementia." (PMID 41185962, 2025). "For example, a recent study identified EDA2R as a potential biomarker for dementia among participants from the English Longitudinal Study of Ageing (ELSA) through a population-based proteomics approach." (PMID 40295347, 2025).
diabetes (3 papers, 2022 to 2023). "Interestingly, the EDA-A2/EDA2R complex has been implicated in the regulation of glucose metabolism in individuals with diabetes mellitus, and serum EDA-A2 levels have been related to BMI and obesity." (PMID 36964401, 2023). "Meanwhile, analysis of the correlation between EDA2R and circHIPK3 transcriptional levels showed that EDA2R was positively correlated with circHIPK3 expression in glomeruli micro-dissected from diabetic kidneys." (PMID 36263181, 2022). "Furthermore, EDA2R was also found to be highly expressed in podocytes treated with high glucose concentration in vitro and in glomerular podocytes of diabetes patients." (PMID 37091044, 2023).
hypohidrotic ectodermal dysplasia (3 papers, 2024 to 2025). A genetic disorder of ectoderm development characterized by malformation of ectodermal structures such as skin, hair, teeth and sweat glands. "The EDA2R plays an important role in the maintenance of hair and teeth, and the variations in this gene can cause hypohidrotic ectodermal dysplasia (HED) in humans, which is characterized by abnormal development of the teeth, hair, and sweat glands." (PMID 39092175, 2024). "In addition, FoxO1 induced the expression of ectodysplasin A (Eda) and its receptor Eda2r, which are known to be associated with X-linked hypohidrotic ectodermal dysplasia and are involved in salivary gland development in myoepithelial cells." (PMID 38212454, 2024). "Mutations in EDA2R have been causally linked to non‐syndromic forms of hypohidrotic ectodermal dysplasia (HED), a condition characterised by abnormalities in hair, sweat glands and teeth." (PMID 41185962, 2025).
Obesity (3 papers, 2023 to 2025). Accumulation of substantial excess body fat. "Elevated EDA2R gene expression is associated with accelerated ageing, cellular senescence, frailty, obesity, acne, radiation response and increased levels of inflammatory, renal, cardiac and vascular biomarkers." (PMID 41185962, 2025). "This pilot study indicates that the plasma proteins alpha-2-MRAP, HAGH, Siglec-9, MDGA1, EDA2R, and IL12 are negatively associated with cognitive performance in a sample of older adults with overweight/obesity and MetS." (PMID 36964401, 2023). "Similarly, EDA2R, a member of the TNF receptor family, was highlighted as a significant marker for cardiometabolic aging due to its association with obesity, insulin resistance, and muscle atrophy." (PMID 40295347, 2025). "Here, we showed a significant increase in NPX in 6 proteins (alpha-2-MRAP, HAGH, Siglec-9, MDGA1, EDA2R, and IL12) in the l-GCF group of older adults with overweight/obesity and MetS from the PREDIMED-Plus cohort." (PMID 36964401, 2023).
prostate carcinoma (3 papers, 2017 to 2025). A carcinoma that arises from epithelial cells of the prostate gland. "Genetic variants of EDA2R are linked to alopecia, facial ageing, lipid profiles and prostate cancer." (PMID 41185962, 2025). "Here, our analysis confirmed the positive epidemiological association between prostate cancer and MPB at Xq12 (AR/EDA2R-locus), pointing towards a shared pathophysiological mechanism that may involve EDA2R-signalling and AR-transactivation." (PMID 28272467, 2017).
Alzheimer disease (2 papers, 2025). A progressive, neurodegenerative disease characterized by loss of function and death of nerve cells in several areas of the brain leading to loss of cognitive function such as memory and language. "These discoveries from ELSA were robustly replicated in the UKB, where NEFL, MMP12, KIM1 and EDA2R were significantly associated with ACD, Alzheimer’s disease and VAD." (PMID 40092369, 2025). "There was evidence suggesting that Alzheimer’s disease [β (se): 0.013 (0.049); P = 0.007 (based on IVW)], ACD [β (se): −0.032 (0.012); P = 0.007 (based on IVW)] and VAD [β (se): −0.036 (0.012); P = 0.003 (based on weighted median)] might have a causal link to altered EDA2R abundance." (PMID 40092369, 2025).
cognitive decline (2 papers, 2025). "They identified protein signatures predictive of cognitive decline, highlighting seven proteins, including EDA2R, consistently associated across multiple cognitive domains." (PMID 41185962, 2025). "Multiple studies have implicated EDA2R in cognitive decline and neurodegeneration." (PMID 41185962, 2025). "In our sDS cohort, EDA2R overexpression could therefore contribute to cognitive decline via chronic reactive astrogliosis." (PMID 40110647, 2025).
sarcopenia (2 papers, 2025). Progressive decline in muscle mass due to aging which results in decreased functional capacity of muscles. "We further demonstrate its functional relevance in skeletal muscle, where increased EDA2R expression induces parainflammatory responses, mimicking aspects of aging-driven sarcopenia." (PMID 39988718, 2025). "Additionally, the review assesses the therapeutic potential of targeting EDA2R to mitigate inflammation, promote healthy ageing and treat conditions such as alopecia, sarcopenia, neurodegeneration and cardiovascular disease." (PMID 41185962, 2025). "We show that strengthening of the Ectodysplasin-A2-Receptor signalling axis in myogenic precursors and differentiated myotubes suffices to trigger potent parainflammatory responses, mirroring aspects of aging-driven sarcopenia." (PMID 39988718, 2025).
acne (1 paper, 2025). An inflammatory process of the sebaceous glands which is characterized by comedones, nodules, papules and/or pustules on the skin. "EDA2R has also emerged as a significant biomarker in skin‐related disorders, including acne and sebaceous gland dysfunction." (PMID 41185962, 2025).
baldness (1 paper, 2017). "The top X chromosome gene-based findings included the androgen receptor (AR), which has been well established as a baldness associated gene, along with its upstream (EDA2R) and downstream (OPHN1) genes." (PMID 28196072, 2017).
colitis (1 paper, 2021). Inflammation of the colon. "In colitis crypts, a notable cytokine–cytokine receptor, miR-494-3p-targeted EDA2R and the ligand EDA-A2, suppressed colonic stemness and epithelial repair by inhibiting β-catenin/c-Myc." (PMID 33594251, 2021). "To determine the potential clinical significance of miR-494-3p/IKKβ or EDA-A2/EDA2R in IBD, we analyzed the levels of miR-494-3p, IKKβ, and EDA-A2/EDA2R in experimental colitis and in patients with active IBD." (PMID 33594251, 2021). "In addition, our data revealed that the levels of EDA-A2 and EDA2R were enhanced in DSS-induced colitis as well as in active IBD samples." (PMID 33594251, 2021). "They find that a cytokine–cytokine receptor, miR-494-3p-targeted EDA2R and its ligand EDA-A2 derived from macrophages, suppresses colonic stemness and epithelial repair in colitis crypts." (PMID 33594251, 2021). "Therefore, our data demonstrate that the administration of miR-494-3p agomir protects mice from DSS-induced colitis and further show that miR-494-3p negatively correlates with IKKβ and EDA-A2/EDA2R in patients with active IBD." (PMID 33594251, 2021).
COVID-19 (1 paper, 2021). A disease caused by infection with severe acute respiratory syndrome coronavirus 2. "Correlation analysis identified SCARB2 is most correlated with tau and GFAP, and EDA2R is most correlated with Nfl, suggesting that these novel proteins are associated with COVID-19-related early or later CNS injury, respectively." (PMID 33737684, 2021).
diabetic nephropathy (1 paper, 2023). "EDA2R may aggravate the development of diabetic nephropathy by regulating podocyte apoptosis and dedifferentiation and increasing ROS production." (PMID 37091044, 2023).
glaucoma (1 paper, 2026). Increased pressure in the eyeball due to obstruction of the outflow of aqueous humor. "After comprehensive adjustment, 136 proteins were significantly associated with glaucoma risk (false discovery rate < 0.05), with EDA2R showing the strongest association (hazard ratio [HR] = 1.21, 95% confidence interval [CI] = 1.16-1.25, P = 2.99 × 10-17)." (PMID 41789843, 2026).
lung adenocarcinoma (1 paper, 2023). A carcinoma that arises from the lung and is characterized by the presence of malignant glandular epithelial cells. "However, patients with increased EDA2R expression exhibited a better prognosis in lung adenocarcinoma, liver hepatocellular carcinoma, and sarcoma." (PMID 37904416, 2023).
Lymphatic Metastasis (1 paper, 2021). Transfer of a neoplasm from its primary site to lymph nodes or to distant parts of the body by way of the lymphatic system. "The expression levels of RELT, TNFSF18, and TNFRSF25 were high, and the expression levels of EDA2R were low in patients with lymphatic metastasis." (PMID 34484286, 2021).
mucositis (1 paper, 2017). Mucositis is inflammation and damage of the mucous membranes lining the mouth and other parts of the gastrointestinal (GI) tract. "However, the gene alterations associated with apoptosis observed in our study, including EDA2R, did not depend on the level of clinical mucositis." (PMID 28052121, 2017).
multiple myeloma (1 paper, 2025). "They found that elevated levels of EDA2R protein were positively associated with diffuse lymphoma, liver cancer, lung cancer, multiple myeloma, non‐Hodgkin lymphoma, lip and oral cavity cancer, lung adenocarcinoma, lung small cell carcinoma and lung squamous cell carcinoma." (PMID 41185962, 2025).
muscle atrophy (1 paper, 2024). The loss of muscle tissue due to inactivity or disease. "Muscle atrophy‐related genes, including Atrogin1, MuRF1 and Eda2r, were upregulated in these myonuclei, emphasizing their crucial roles in muscle wasting." (PMID 39001644, 2024).
ovarian carcinoma (1 paper, 2024). A malignant neoplasm originating from the surface ovarian epithelium. "The enhanced expression of EDA2R in specimens may explain an unfavorable prognosis in ovarian cancer with wild-type TP5346." (PMID 38584220, 2024).
ovarian tumors (1 paper, 2021).
periodontitis (1 paper, 2023). An acute or chronic inflammatory process that affects the tissues that surround and support the teeth. "In the Pg sample, we observed interactions between ADM and CALCRL, which is related to periodontitis; EDA and EDA2R, which is related to ectodermal development; and SPP1 and CD44 and SPP1 and (ITGA4+ITGB1), which promotes phosphoprotein secretion and regulates bone salinization." (PMID 37287452, 2023).
cancer (15 papers, 2017 to 2025). A tumor composed of atypical neoplastic, often pleomorphic cells that invade other tissues. "In addition, high EDA2R levels were associated with increased risk of all‐cause mortality and cause‐specific mortality related to cancer, nervous, circulatory and respiratory system diseases." (PMID 41185962, 2025). "Interestingly, tumour‐induced alterations in the expression of Atrogin1, MuRF1, Pik3r1, Pdk4, Myh4, Myh2 and Myh1 were attenuated in EDA2R‐deficient muscles, implying that the EDA2R pathway contributes to the reprogramming of muscle gene expression during cancer cachexia." (PMID 39001644, 2024). "This includes several potential cancer related genes like EDA2R (minimum p-value = 3.7×10−31), and multiple other members of the tumor necrosis factor receptor superfamily like TNFRSF11B (minimum p-value = 1.3×10−12) and TNFRSF8B (minimum p-value = 1.1×10−13)." (PMID 41404623, 2025). "The ANRS consists of five ANRGs: SPIB, CD24, NTRK3, EDA2R, and PLK1, all of which have been extensively linked to cancer." (PMID 39596658, 2024). "EDA2R mediates the activation of NF-κB and JNK pathways and is closely associated with cancer cachexia." (PMID 38988712, 2024). "Little is known about the effects of melphalan on normal epithelium, but in cancer cells, melphalan induces oxidative stress and upregulates a wide range of apoptosis-related genes, consistent with our findings of EDA2R upregulation." (PMID 28052121, 2017). "As a tumor suppressor, EDA2R prevents malignant transformation and cancer progression." (PMID 35186006, 2021).